AMH (anti-Mullerian hormone)
Diseases named in the same sentence as AMH in open-access papers (continued):
Sharing a sentence is not in itself a finding about the gene and the disease.
breast tumor (2 papers, 2017 to 2025). "In humans, AMH had an inverse relationship with breast tumor development and growth." (PMID 29180824, 2017).
cervical carcinoma (2 papers, 2019 to 2025). A carcinoma arising from either the exocervical squamous epithelium or the endocervical glandular epithelium. "Previous research has shown that in cervical cancer, AMH can influence cancer cell apoptosis by modulating cell cycle progression." (PMID 41387944, 2025). "Due to the activity of AMH, the levels of p16, p107 and p130 increase in cervical carcinoma cells." (PMID 30884769, 2019).
chronic kidney disease (2 papers, 2017 to 2022). Impairment of the renal function secondary to chronic kidney damage persisting for three or more months. "Similarly, end-stage renal disease was uncommon in the EDIC cohort, and it is possible that the relationship between AMH and renal disease would have been more pronounced in a population with a higher incidence of disease." (PMID 30766706, 2017).
congenital adrenal hyperplasia (2 papers, 2016 to 2022). Congenital adrenal hyperplasia (CAH) is an inherited endocrine disorder caused by a steroidogenic enzyme deficiency that is characterized by adrenal insufficiency and variable degrees of hyper or hypo androgyny manifestations, depending of the type and the severity of the disease. "In 46,XX DSD patients with ambiguous external genitalia, AMH levels above the normal female range exclude the diagnosis of congenital adrenal hyperplasia, aromatase defects or virilizing tumors, and are highly suggestive of an Ovotesticular DSD." (PMID 27799946, 2016).
endometrial tumors (2 papers, 2021 to 2022). "This was not been confirmed in our studies, where the baseline AMH was significantly higher in endometrial tumors than in other tumors." (PMID 36676638, 2022).
endometrioid adenocarcinoma (2 papers, 2019 to 2021). An adenocarcinoma characterized by the presence of malignant glandular epithelial cells resembling endometrial cells. "AMH expression was confirmed in 23 patients with well differentiated endometrioid adenocarcinoma (G1), moderately differentiated endometrioid adenocarcinoma (G2), clear cell carcinoma (CCA) and nonatypical hyperplasia." (PMID 30884769, 2019).
endothelial dysfunction (2 papers, 2017 to 2024). In vascular diseases, endothelial dysfunction is a systemic pathological state of the endothelium (the inner lining of blood vessels) and can be broadly defined as an imbalance between vasodilating and vasoconstricting substances produced by (or acting on) the endothelium. "Aldosterone angiotensin renin is suppressed by COVID-19, which can cause various disorders, including endothelial dysfunction, inflammation, damage to the reproductive system, and ultimately, reduced levels of AMH." (PMID 39906086, 2024).
epilepsy (2 papers, 2022 to 2024). A brain disorder characterized by episodes of abnormally increased neuronal discharge resulting in transient episodes of sensory or motor neurological dysfunction, or psychic dysfunction. "21.7% patients had a family history of PCOS while none had a history of epilepsy needing anti-epileptic medications of maternal anti mullerian hormone (AMH) administration in the second trimester." (PMID 36411444, 2022).
gonadal dysgenesis (2 papers, 2016 to 2024). A congenital disorder characterized by the presence of extremely hypoplastic gonads preventing the development of secondary sex characteristics. "Hormonal evaluations in prepubertal boys may also help to identify the underlying causes of testicular descent disorders, such as gonadal dysgenesis, disorders of androgen synthesis, androgen insensitivity, or disruptions in AMH and INSL3 production or action." (PMID 39797156, 2024). "While testosterone is low in both situations, serum AMH is helpful to establish a differential diagnosis since it is low in patients with gonadal dysgenesis but normal or high in patients with isolated androgen deficiency." (PMID 27799946, 2016).
Gonadotropin deficiency (2 papers, 2022 to 2023). A reduced ability to secrete gonadotropins, which are protein hormones secreted by gonadotrope cells of the anterior pituitary gland, including the hormones follitropin (FSH) and luteinizing hormone (LH). "In women with FHA without PCOM, the phenomenon of low AMH levels seems to be based on relative gonadotropin deficiency rather than diminished ovarian reserve." (PMID 35787707, 2022). "In these FHA patients, AMH tends to rise after three months of pulsatile GnRH treatment and this seems to be associated with a rise in FSH, which underlines that the phenomenon of low AMH levels is based on relative gonadotropin deficiency rather than diminished ovarian reserve." (PMID 35787707, 2022).
gynecological cancer (2 papers, 2019 to 2024). "In several gynecological cancers, anti‐Müllerian hormone receptor type 2 (AMHR2) mediates AMH‐induced growth inhibition and is expressed at high levels." (PMID 39230026, 2024).
lymph node metastases (2 papers, 2021). "Additionally, higher AMH expressions were related to higher Gleason score, lymph node metastasis and positive rate, and tumor stages, and higher ATGR1 expressions were related to lower PSA value." (PMID 34568039, 2021). "Additionally, higher AMH expressions were related to higher Gleason scores, lymph node metastasis rates, tumor grades, and lower positive lymph nodes." (PMID 34568039, 2021).
macrosomia (2 papers, 2021 to 2023). "In singleton delivery, an decreased risk of macrosomia was found in the low AMH group compared with the average AMH group (aOR1 = 0.65, 95%CI: 0.48-0.89), while the high AMH group showed a similar effect (aOR2 = 0.72, 95%CI: 0.57-0.96)." (PMID 36896183, 2023). "There are also some protective factors, for instance, among women of singleton delivery, high AMH levels are associated with a lower risk of macrosomia as well as low levels of AMH are less likely to have PROM and LGA." (PMID 36896183, 2023). "In addition, AMH can also be used as a protective factor concerning PROM, macrosomia and LGA." (PMID 36896183, 2023). "However, among PCOS patients with a BMI ≥24 kg/m2, serum AMH>6.45 ng/ml (75th percentile) is an independent risk factor for PTB but not an independent risk factor for SGA, LBW, macrosomia, or LGA." (PMID 34956097, 2021).
malaria (2 papers, 2021 to 2022). Malaria is a serious and sometimes fatal disease caused by a parasite that commonly infects a certain type of mosquito which feeds on humans. "In an analysis of AMH levels of South African women, researchers found that women exposed to pyrethroids from indoor pesticide spraying for malaria control had a 25% lower AMH (95% CI: −39, −8) than those who were not exposed." (PMID 35627519, 2022).
McCune-Albright syndrome (2 papers, 2016 to 2022). McCune-Albright syndrome (MAS) is classically defined by the clinical triad of fibrous dysplasia of bone (FD), cafe-au-lait skin spots, and precocious puberty (PP). "These molecular mechanisms explain the elevated AMH production observed in boys with McCune-Albright syndrome carrying a gain-of-function somatic mutation in the GNAS1 gene encoding the Gαs protein." (PMID 35712256, 2022). "Finally, elevation of serum AMH above normal male prepubertal levels may be indicative of rare cases of sex-cord stromal tumors or Sertoli cell-limited disturbance in the McCune Albright syndrome." (PMID 27799946, 2016). "Conversely, high AMH is suggestive of Sertoli cell tumors, excessive signaling downstream the FSH receptor pathway like in McCune-Albright syndrome, or hyperestrogenism." (PMID 35712256, 2022).
meningioma (2 papers, 2023 to 2025). A generally slow growing tumor attached to the dura mater. "Interestingly, ISLR2, AMH, and lncRNA-GOLGA6A-1 transcription is controlled by several transcription factors including KLF4, which is linked to activating mutations of meningiomas." (PMID 38001599, 2023).
polymyositis (2 papers, 2019 to 2025). A rare idiopathic inflammatory myopathy characterized by symmetric proximal muscle weakness and elevated muscle enzymes. "Our results are in line with those obtained in women with polymyositis (PM) where serum AMH resulted significantly lower in comparison to controls while the number of the AFC was similar in both groups." (PMID 39576415, 2025).
puberty (2 papers, 2016). The process of sexual maturation mediated by the neuroendocrine system in mammals. "Important challenges in the near future are to determine whether alterations of the pituitary AMH system may be related to some puberty disorders." (PMID 27030385, 2016).
Sertoli Cell-Only Syndrome (2 papers, 2013 to 2022). A type of male infertility in which no germ cells are visible in any of the biopsied SEMINIFEROUS TUBULES (type I) or in which germ cells are present in a minority of tubules (type II). "Notably, however, high-level AMH expression can be detected in the immature Sertoli cells of adult patients with Sertoli-cell-only syndrome (SCOS) or AIS." (PMID 24098470, 2013).
sex cord tumors (2 papers, 2019 to 2021). "monitored serum AMH levels during a 54-month follow-up of a patient diagnosed with a sex-cord tumor and demonstrated that the serum concentration of AMH correlated with the degree of AGCT growth and tumor recurrence." (PMID 33828986, 2021). "The highest reported serum AMH concentration of 3205.93 ng/mL was found in a patient with sex cord tumor in whom remote metastases were present." (PMID 30884769, 2019). "Furthermore, the serum AMH determination is useful to control the progress of ovarian granulosa cell and sex cord tumors." (PMID 30884769, 2019).
Testicular atrophy (2 papers, 2015 to 2025). Wasting (atrophy) of the testicle (the male gonad) manifested by a decrease in size and potentially by a loss of fertility. "An increased expression of markers of immaturity in Sertoli cells, including AMH, has recently been described in cases of canine testicular atrophy." (PMID 26209243, 2015). "Because AMH concentrations are increased in dogs with SCT, as shown in the present study, and an elevated expression of AMH has been described in testicular degeneration, analysis of AMH is of potential value in the diagnostic workup of dogs with reduced fertility." (PMID 26209243, 2015).
testicular tumors (2 papers, 2015 to 2016). "Whereas AMH is produced solely by Sertoli cells, increased production of oestradiol can be caused also by other testicular tumours but most commonly by SCTs." (PMID 26209243, 2015). "The aim of the present study was to evaluate the clinical relevance of AMH analysis in peripheral blood in the diagnostic workup of dogs with suspected testicular tumours." (PMID 26209243, 2015). "AMH immunohistochemistry is useful to identify the sex-cord stromal origin in testicular tumors." (PMID 27799946, 2016).
adrenal cortical tumours (1 paper, 2025). "AMH testing can be useful in the diagnosis of ORS and, in some cases, ruling out differential diagnoses such as adrenal cortical tumours, as AMH is secreted exclusively by ovarian tissue." (PMID 41227437, 2025).
adrenal tumour (1 paper, 2025). "Moreover, while AMH may be particular useful when adrenal tumour secretes only oestrogens, its diagnostic value becomes limited if the tumours secrete only progesterone." (PMID 41227437, 2025). "In such cases, measuring both progesterone and AMH may not allow a clear distinction between ORS and adrenal neoplasia, since both false-negative AMH result due to luteal tissue and a negative AMH result in presence of a steroid-secreting adrenal tumour could lead to diagnostic uncertainty." (PMID 41227437, 2025).
alopecia (1 paper, 2015). Hair loss usually from the scalp. "The present study aimed at evaluating the clinical relevance for analysis of AMH in the diagnostic workup of dogs with alopecia or other clinical signs suspected to be associated with Sertoli cell tumours." (PMID 26209243, 2015). "An elevated serum concentration of AMH associated with SCT has previously been reported in a dog with non-pruritic alopecia." (PMID 26209243, 2015).
asthenospermia (1 paper, 2021). "Similar to our study, serum AMH of patients with normal spermatozoa or mild asthenospermia (IVF group) appears to be extremely higher than serum AMH of patients with moderate oligozoospermia (R‐ICSI group)." (PMID 34270116, 2021).
autism spectrum disorder (1 paper, 2015). A spectrum of developmental disorders that includes autism, and Asperger syndrome. "Regarding the AMH gene, with DS-DM in cerebral and cerebellar cortex, circulating anti-Mullerian hormone levels correlate to performance on social aptitude tests among individuals with autism spectrum disorder, and sex-dependent cognitive phenotypes have been demonstrated in DS." (PMID 26607552, 2015).
bone metabolism disorders (1 paper, 2026). "Additionally, as a key factor linking ovarian function and bone health, the AMH research concepts and methods summarized herein can be extended to other hormone-related bone metabolism disorders." (PMID 41751326, 2026).
clear cell carcinoma (1 paper, 2019). "This justifies undertaking further research on AMH expression and a 5-year survival period in patients with clear cell carcinomas." (PMID 30884769, 2019).
coronary artery calcification (1 paper, 2017). Calcification of the coronary artery, used as a measure of coronary atherosclerosis, a risk factor for myocardial infarction. "We also examined whether initial AMH concentrations were associated with the presence of any coronary artery calcification (CAC) or carotid intima media thickness (cIMT)." (PMID 30766706, 2017).
coronary heart disease (1 paper, 2025). "Currently, it has been suggested that AMH levels and its decline rate can be a probable contributor to CVDs and coronary heart disease among women independent of menopausal condition and metabolic risk factors." (PMID 40708780, 2025).
Cryptozoospermia (1 paper, 2023). A type of oligozoospermia in which spermatozoa can be detected in an ejaculate only after centrifugation and inspection of the pellet. "The median AMH of the spouse was 3.57 ng/mL (0.00–15.10) in cryptozoospermia cases and 3.49 ng/mL (0.24, 14.59) in TESE." (PMID 37900700, 2023).
Delayed puberty (1 paper, 2021). Passing the age when puberty normally occurs with no physical or hormonal signs of the onset of puberty. "Also consistent with a negative correlation with testosterone concentrations, males with delayed puberty exhibit significantly elevated AMH levels, whilst males experiencing a precocious puberty have serum AMH concentrations substantially lower than those of age-matched peers." (PMID 34557157, 2021).
dyskeratosis congenita (1 paper, 2021). Dyskeratosis congenita (DC) is a rare ectodermal dysplasia that often presents with the classic triad of nail dysplasia, skin pigmentary changes, and oral leukoplakia associated with a high risk of bone marrow failure (BMF) and cancer. "In Dyskeratosis congenita (DKC), canonical human telomeropathy is characterized by low telomerase activity and short telomeres, and women display diminished ovarian reserves, as estimated by circulating levels of anti-Mullerian hormone and impaired reproductive function." (PMID 34356906, 2021).
Dysmenorrhea (1 paper, 2023). Pain during menstruation that interferes with daily activities. "However, our analysis did not provide any evidence of a causal effect of female coffee consumption on their levels of TT, E2, and AMH (respectively) or on the incidence of irregular menstrual cycle/bleeding and dysmenorrhea." (PMID 37091804, 2023). "However, no causal effects were found between alcohol drinking and SHBG, bio-T, E2, and AMH levels (respectively), as well as irregular menstrual cycle/bleeding and dysmenorrhea (respectively), even after the heterogeneity and horizontal pleiotropy were eliminated." (PMID 37091804, 2023).
esophageal squamous cell carcinoma (1 paper, 2021). Esophageal squamous cell carcinoma (ESCC) is a type of esophageal carcinoma (EC) that can affect any part of the esophagus, but is usually located in the upper or middle third. "AMH mutations has been identified in esophageal squamous cell carcinoma and gastric cancer." (PMID 33437203, 2021).
euthyroid sick syndrome (1 paper, 2022). Abnormal thyroid function tests, low triiodothyronine with elevated reverse triiodothyronine, in the setting of non-thyroidal illness. "Perhaps, similar to the euthyroid sick syndrome, systemic inflammation in FMF may reduce the effect of AMH on antral follicles." (PMID 36134042, 2022).
Ewing sarcoma (1 paper, 2016). A small round cell tumor that lacks morphologic, immunohistochemical, and electron microscopic evidence of neuroectodermal differentiation. "We prospectively investigated anti-Müllerian hormone (AMH) as a measure of ovarian insult in young females during and after treatment for Wilms tumor (WT), osteosarcoma (OS), and Ewing sarcoma (ES)." (PMID 27537574, 2016).
fertilization disorders (1 paper, 2022). "The laboratory model, including AMH, showed a higher AUC (0.742 to predict TFF) than reported previous prediction models for fertilization disorders in ART." (PMID 35518924, 2022).
fibrosis (1 paper, 2025). the formation of excess fibrous connective tissue in an organ or tissue in a reparative or reactive process. "Ovarian reserve: Fibrosis and oxidative damage caused by endometriomas underlie reductions in the antral follicle count (AFC) and the levels of anti-Müllerian hormone (AMH)." (PMID 40906150, 2025).
Follicular Cyst (1 paper, 2017). Cyst due to the occlusion of the duct of a follicle or small gland. "In addition, human infant ovaries exhibited follicular cysts (9–10 mm in diameter) consisting of a large cavity surrounded by a thick layer of thecal cells that displayed neither AMH nor aromatase expression." (PMID 28397811, 2017).
germ cell tumor (1 paper, 2014). A benign or malignant, gonadal or extragonadal neoplasm that originates from germ cells. "In the pre-operative workup, the dosages of serum markers AFP, HCG, AMH, beta HCG, and LDH are useful because the germ cell tumors are produced by them." (PMID 24982844, 2014).
gonadotropin-independent precocious puberty (1 paper, 2016). "Like in normal puberty, serum AMH declines in boys with central or gonadotropin-independent precocious puberty, showing the well-known inhibition exerted by androgens on Sertoli cell AMH production." (PMID 27799946, 2016).
Gynecomastia (1 paper, 2021). Abnormal development of large mammary glands in males resulting in breast enlargement. "This patient showed a relatively developed penis (length of 4 cm), no gynecomastia, extremely elevated serum LH (51.33 mIU/ml) and FSH (79.94 mIU/ml) levels, relatively lower T (2.8 ng/ml, normal range 1.42–9.23 ng/ml) level and significantly reduced AMH level (0.44 ng/ml)." (PMID 33750429, 2021).
Hodgkins lymphoma (1 paper, 2023). A heterogeneous group of malignant lymphoid neoplasms of B-cell origin characterized histologically by the presence of Hodgkin and Reed-Sternberg (HRS) cells in the vast majority of cases. "In patients treated for Hodgkin lymphoma, AMH serum levels decreased during chemotherapy, more profoundly after BEACOPP than after ABVD, with a reciprocal increase of FSH." (PMID 37766870, 2023).
hypercortisolism (1 paper, 2023). "Anti-Müllerian hormone (AMH), produced in the granulosa cells of the ovary, is raised in polycystic ovarian syndrome (PCOS), so it may be helpful in discriminating mild hypercortisolism and PCOS, which can be difficult clinically." (PMID 37189516, 2023).
hyperprolactinaemia (1 paper, 2023). "AMH level was lower (3.57 ± 1.7 vs. 3.22 ± 3.14 ng/ml; p = 0.025), and prolactin level was slightly higher (14.17 ± 4.92 vs. 21.69 ± 14.3, p = 0.007) in patients with hyperprolactinaemia, both within the normal range." (PMID 36477597, 2023).